ERLNC1 (estrogen receptor responsive lncRNA 1)
Synonyms: TC0101441; ElncRNA1
Gene: Long non-coding RNA gene on chromosome 1 (204,141,404 to 204,143,327, forward strand). Ensembl gene ENSG00000230550.
Diseases named in the same sentence as ERLNC1 in open-access papers:
ERLNC1 is named in the same sentence as 2 diseases in open-access papers, as found by Europe PMC text mining. Sharing a sentence is not in itself a finding about the gene and the disease.
ERLNC1 shares sentences with these, for which no sentence is quoted: endometriosis (1 paper); epithelial ovarian cancer (1).